EIF4E (eukaryotic translation initiation factor 4E)
Diseases named in the same sentence as EIF4E in open-access papers (continued):
Sharing a sentence is not in itself a finding about the gene and the disease.
cancer (continued). "The idea of using cap analogues for therapeutic purposes came with reports that an elevated level of eIF4E is associated with tumor formation and progression in human malignancies and cancers of the breast, colon, bladder, prostate, lung, head, and neck (the top row)." (PMID 38794202, 2024). "Phosphorylation of eIF4E is linked to cancer development and progression." (PMID 39111820, 2024). "MYC, an oncogenic transcription factor upregulated in various cancers, has been implicated in regulating protein synthesis by regulating ribosome biogenesis and the abundance of tRNAs or modulating translation factors, including eIF4F, eIF4E, eIF4G, and eIF4A." (PMID 38273337, 2024). "Since eIF4E has been implicated in cancer, the upregulation of eIF4E1c may contribute to the rare development of tumor-like gonads without oocytes in eif4e1b mutant fish." (PMID 38177902, 2024). "Indeed, dysregulation of eIF4E and metabolism are hallmarks of cancer, emphasizing the importance of understanding the underlying mechanisms to develop effective therapeutic strategies." (PMID 37214807, 2023). "EIF4E has also been associated with therapeutic resistance in a variety of cancers." (PMID 37631029, 2023). "Phosphorylation of eIF4E on serine 209 by MNKs is associated with tumor progression and poor prognosis, with high levels of phosphorylated eIF4E (p-eIF4E) found in different types of cancer." (PMID 37111758, 2023). "Abnormal eIF4E expression has been linked to cancer susceptibility and malignant transformation." (PMID 34944630, 2021). "eIF4E overexpression causes a loss of contact inhibition, one of the hallmarks of cancer." (PMID 33375634, 2020). "In univariate and multivariate (model 1) Cox regression analyses, pT1b≤ stage (vs. pT1a), Fuhrman grade 3/4 (vs. grade 1/2), presence of coagulative necrosis (vs. absence), and high eIF4E expression (vs. low) were significantly related to a high risk of recurrence and cancer-specific mortality." (PMID 31258849, 2019). "However, direct targeting of Eif4e for enhancing neuronal regeneration would be a high-risk strategy, since increasing Eif4e levels or activity promotes cellular transformation and cancer cell survival." (PMID 29756027, 2018). "Thus, our data confirmed that loss of Hsp27/eIF4E interaction via truncation of Hsp27 C-terminal region restores chemo- and hormone- sensitivity in cancer cells." (PMID 29100389, 2017). "The first RBP to be linked to cancer was eukaryote initiation factor 4E (eIF4E), when investigators demonstrated that its ectopic expression could drive malignant transformation in fibroblasts and mammalian epithelial cells." (PMID 26501340, 2015). "Indeed, it has been known for some time that certain translational factors, notably eIF4E, are downstream targets of various signaling pathways that control cell migration, and its over-expression is causative of cancer progression." (PMID 25886394, 2015). "Deregulation of multiple elements of the mTOR pathway (PI3K amplification/mutation, PTEN loss of function, AKT overexpression, and S6K1, 4EBP1 and eIF4E overexpression) has been reported in cancer, such as breast, ovarian, renal, colon and head and neck cancers." (PMID 22408430, 2012). "However, eIF4E’s mRNA export functions are also critical for its oncogenic activities, as shown by mutational studies dissecting the role of translation and export and their relative impact on cancer." (PMID 33375634, 2020). "Importantly, CADPE dramatically downregulates the levels of eIF4E, eIF4G, and eIF4A, thus leading to the impairments of Cap-dependent translation and the eIF4G- or eIF4A-driven alterative translations that have been shown to cause cancer treatment failure." (PMID 33191401, 2020). "Since eIF4E protein is overexpressed in 30% of cancers, it acts as a reference translation initiation factor associated with the translation of genes involved in proliferation, e.g. cyclin D1 or c-myc, stimulating proliferation of cancer cells when overexpressed." (PMID 31825993, 2019).
cancer (continued). "Therefore, we hypothesized that cancer-associated nuclear bodies as detected by p-eIF4E antibody may exist in the nuclei of cancer cells." (PMID 26678034, 2016). "Since some of these latter factors would make cancer cells become more proliferative and invasive, our findings may explain the significant association of vascular invasion and a worsened clinical outcome in patients having marked eIF4E expression." (PMID 17010208, 2006). "eIF4E is a protooncogene, key for cell signaling in cancer, and is overexpressed in different tumors, including PCa." (PMID 41009328, 2025). "Experimental studies have shown that downregulating eIF4E expression in cancer cells diminishes their proliferative and transformative properties, highlighting eIF4E pivotal role in oncogenesis." (PMID 41208200, 2025). "MAPK-interacting kinases (MNKs) are involved in the phosphorylation of initiation factor 4E (eIF4E), where their protein pathway MNK1/2 eIF4E is overexpressed in cancer cells." (PMID 40872614, 2025). "There is increasing understanding that the activity of eIF4E is abnormally increased to stimulate cell growth, proliferation, and translation of related proteins in cancer initiation and development." (PMID 40308810, 2025). "Inhibition of the eIF4E factor induced tumor control, indicating RNA nuclear export as a druggable target in cancer." (PMID 41440011, 2025). "These inhibitors, including initial MNK 1/2 inhibitor cercosporamide, were found to effectively block eIF4E phosphorylation and induce anti-tumour activity in various preclinical cancer models." (PMID 40805230, 2025). "ATP-competitive mTOR inhibitors markedly reduce phosphorylated 4E-BP1 and can effectively prevent eIF4E-mediated cap-dependent translation initiation in cancer." (PMID 40563640, 2025). "The 4EBP1 inhibitor antagonizes eIF4E by signal transduction pathways that phosphorylate and inactivate of 4EBP1, suggesting the potential importance of eIF4E as a MYC regulatory target in cancer." (PMID 39779613, 2025). "In certain types of cancers, the eIF3d and eIF4G2 driven mechanism is also used to bypass the global sequestration of eIF4E, thereby allowing EMT, which is a crucial indicator for cancer progression to occur." (PMID 39971159, 2025). "Preclinical studies have demonstrated that eIF4E inhibitors can effectively reduce the growth and proliferation of cancer cells." (PMID 40225856, 2025). "Decades of work have gone into creating eIF4E inhibitors since it is believed that carcinogenic mRNAs have the greatest eIF4E demand for translation in the genesis of cancer." (PMID 40225856, 2025). "The role of translation initiation factors in cancer has garnered increasing attention, yet prior studies predominantly focused on upstream regulators like eIF4E or phosphorylated eIF2α." (PMID 41144132, 2025). "A rational covalency-first approach was described recently targeting eukaryotic translation initiation factor 4E (eIF4E), an mRNA cap-binding protein (like DcpS) that stimulates the translation of proteins involved in cancer cell proliferation and metastasis." (PMID 40443986, 2025). "Hyperactive eIF4E-dependent translation plays a central role in reprogramming the proteome in cancer cells by supporting the translation of a subset of “eIF4E-sensitive” or “weak” mRNAs with low translation efficiency due to long, structured 5′-UTRs." (PMID 39869680, 2025). "Preclinical findings indicate that eFT508 effectively blocks eIF4E phosphorylation and results in tumour growth inhibition in various cancer models." (PMID 40805230, 2025). "eIF4E variants, which exhibit reduced affinity for the mRNA cap, significantly alter the phenotype of MDA‐MB‐435 cancer cells." (PMID 41208200, 2025). "At present, RBV shows promise in the treatment of specific types of cancers with elevated levels of the eukaryotic translation initiation factor (eIF4E)." (PMID 40076317, 2025).
cancer (continued). "Most ofthe compounds showed a high potency in breast cancer cells (MCF7),characterized by the highest cancer type for overexpression of (p)-eIF4E." (PMID 40385142, 2025). "In the fight against cancer, researchers have turned their attention to the eukaryotic initiation factor eIF4E, a protein whose increased level is strongly correlated with the development and progression of various types of cancer." (PMID 38794202, 2024). "Dysregulation of protein synthesis is a common characteristic of MYC-driven cancers and is marked by increased Pol I-mediated ribosomal rDNA transcription and mTOR/eIF4E-driven mRNA translation." (PMID 39574899, 2024). "mTOR and MNKs activities are frequently up-regulated in cancer to promote the synthesis of pro-tumorigenic proteins by phosphorylating 4E-BPs and eIF4E, respectively." (PMID 39111820, 2024). "These attempts to block eIF4E activity alone or in combination with eIF4G have shown promising results and hold the potential to be developed further to eradicate cancer, wherein cap-dependent translation of specific genes plays a critical role." (PMID 39409166, 2024). "This action facilitates the recognition of the cap structure by Eukaryotic Translation Initiation Factor 4E (eIF4E), leading to an increased synthesis of specific cancer-related proteins and consequently promoting the progression of LC." (PMID 38711100, 2024). "Conversely, the potent oncogene, EIF4E, overexpression accounts for approximately 30% of cancer cases." (PMID 38051091, 2024). "Our findings reveal that these dual modifications increase the potency of the dinucleotide analogue, marking a significant advancement in the development of cancer therapeutics targeting the eIF4E pathway." (PMID 38794202, 2024). "Phosphorylation of eIF4E at the serine 209 leads to the increased global protein translation and is observed in various cancer types." (PMID 38378793, 2024). "The phosphorylation of eIF4e catalyzed by MNK1 induces the translation regulation of mRNAs associated to antiviral response, inflammation, and cancer." (PMID 38303713, 2024). "In cancer cells, the eukaryotic translation initiation factor 4E (EIF4E) controlled translation via PI3K/AKT/mTOR and Ras/MAPK/Mnk signaling pathways." (PMID 38361124, 2024). "Conversely, 4EBP1 acts as a tumor suppressor by inhibiting eIF4E and blocking mRNA translation in various cancers." (PMID 36944636, 2023). "Overall, eIF4E oncogenic activity is primarily due to its capacity to translate a specific subset of mRNAs involved in cancer progression at a higher rate." (PMID 36994107, 2023). "Overexpression of eIF4E has been reported in a variety of cancers, which correlates with the aggressive phenotype of tumors." (PMID 37631029, 2023). "Of note, the lack of activation of the mTORC1/4E-BP1 axis by HBOT turns out to be advantageous, as many investigations related to cancer indicate that activation of the eIF4e axis can lead to tumorigenesis and tumor progression." (PMID 37438828, 2023). "The overexpression of eIF4E plays an up-regulated role in both lipid metabolism and glycolysis, which suggests that overexpression of eIF4E can promote cancer by affecting metabolism." (PMID 37601696, 2023). "EVs derived from human and mouse cells also contain translation initiation factors, such as eIF4E and eIF4G, and some are used as biomarkers for certain cancer types." (PMID 37780856, 2023). "eIF4E is a eukaryotic translation initiation factor and an oncogene with elevated expression in approximately 30% of human cancers." (PMID 37353728, 2023). "RBPs of eukaryotic translation initiation factor 4E (eIF4E) are characterized by cap-binding domains and are well known to induce tumorigenesis and cancer progression." (PMID 37426488, 2023). "The mTORC1/4E-BP/eukaryotic translation initiation factor 4E (eIF4E), a component of the eukaryotic initiation factor 4F complex, is a promising target for cancer treatment and prevention of drug resistance." (PMID 38002277, 2023).
cancer (continued). "In cancer models, phospho-eIF4E regulates translation of targets involved in oncogenic transformation." (PMID 37250335, 2023). "mTOR controls protein synthesis and supports cancer growth by activating S6 and 4EBP1/eIF4E/eIF4A-dependent translation programs." (PMID 36900235, 2023). "Previous studies have revealed that MKNK1 can phosphorylate eukaryotic initiation factor 4E (eIF4E) and co‐regulate various cellular processes, and essentially regulate the progression of different cancers." (PMID 37864471, 2023). "Studies reported that eIF4E, eIF4G and eIF4A genes showed increased amplification or transcription in various human cancers." (PMID 37601696, 2023). "Previously, it was thought that these anti-cancer features were due to the ability to inhibit eIF4E activity through a structural similarity of ribavirin with the mRNA cap structure." (PMID 36994107, 2023). "Due to the relevant role of eIF4E and p-eIF4E in cancer progression, dysregulation of the MNK1/2-eIF4E axis is linked to cancer in a wide spectrum of tissues." (PMID 36994107, 2023). "MNK1/2-mediated eIF4E S209 phosphorylation is believed to be a key event promoting cancer, and MNK1/2-specific inhibitors such as eFT508 are being examined in cancer clinical trials." (PMID 37531320, 2023). "Among the components of the translational machinery, eIF4E is the most studied protein in patients and in both normal and cancer cells." (PMID 36994107, 2023). "There is a common mechanism for eIF4E in different cancers: eIF4E mediates normal cell proliferation, but induces tumorigenesis when it is dysregulated and over expressed." (PMID 37601696, 2023). "Maintaining the level of eIF4E below its cancer promoting threshold is an important anti-cancer measure for normal cells." (PMID 37601696, 2023). "Since the majority of studies support the involvement of p-eIF4E in cancer progression, future studies should investigate the effects of AA on the phosphorylation status of this protein." (PMID 37888706, 2023). "By selectively inhibiting MNK1/2, it plays a role in multiple nodes of the cancer immune cycle, selectively inhibiting eIF4E phosphorylation, thus promoting fat burning." (PMID 37601696, 2023). "For example, mTORC1 signalling is hyperactivated in many cancers, increasing the availability of eIF4E and promoting translation initiation and the translation of a subset of mRNAs (rather than every mRNA)." (PMID 37143925, 2023). "Restraining eIF4E availability by the action of 4E-BP led to a preferential inhibition of translation of weak transcripts with an impact on cancer progression." (PMID 36994107, 2023). "Following NDV-induced PKR-eIF2α-mediated host protein shut-off in human cancer cells, the viral nucleoprotein NP binds to the cellular eIF4E protein within the mRNA translation initiation complex and directs translation exclusively towards viral proteins." (PMID 35327364, 2022). "Rapamycin-induced eIF4E phosphorylation was also found to regulate translation in cancer cells 35-38." (PMID 35813470, 2022). "Using this library and affinity maturation techniques we identify VH domains with picomolar affinity against eIF4E, a protein commonly hyper-activated in cancer." (PMID 35982046, 2022). "Inhibitors targeting upstream PKC and PI3K signaling to induce apoptosis in cancer cells through reducing phosphorylation of 4E-BP1 leads to inhibition of eIF4E and eIF4F activity." (PMID 35626002, 2022). "The results identified statistically elevated eIF4E expression in cancer tissues of LGG and GBM patients compared with normal counterparts (P < 0.05)." (PMID 36225177, 2022). "EIF4E regulates the translation of genes related to ROS and induces transformation and survival in cancer cells." (PMID 35626002, 2022). "Phosphorylated eIF4E (p-eIF4E) has been proved to be overexpressed in many cancers, and be of vital importance in the cancer cell migration/invasion and tumor progression, though its specific mechanism is still elucidated." (PMID 35737644, 2022).
cancer (continued). "To date, although increasing evidences have demonstrated that p-4EBP1 and p-eIF4E play a critical role in cancer, there are limited data evaluating their importance to NSCLC." (PMID 35737644, 2022). "Up-regulation of the abundance and activity of eIF4E occurs widely in cancers and selectively up-regulates translation of certain mRNAs involved in survival, proliferation, and metastasis." (PMID 35869499, 2022). "Inactivation of 4EBP, an inhibitor of eIF4E, by mTORC1-mediated phosphorylation is also a common event in cancer." (PMID 36187485, 2022). "The reduction of eIF4E3 in tumors of elevated eIF4E levels proposed that eIF4E3 identifies a related repressive mechanism in clinical disappearing into a few malignant tumors." (PMID 36118897, 2022). "Numerous studies have elucidated that eIF4E and phosphorylated eIF4E are present in various types of cancer." (PMID 36360287, 2022). "Since eIF4E is also required for Akt-mediated cancers, small molecule inhibitors targeting eIF4E can be also applied to cancer with deregulated Akt activity." (PMID 36180910, 2022). "The ability of the cap-binding protein eukaryotic translation initiation factor 4E (eIF4E) to direct ribosomal translation of the mRNAs is key in the process where a normal cell becomes a cancer cell." (PMID 35454770, 2022). "eIF4E is overexpressed in some human cancers, involving in the mitosis, embryogenesis and apoptosis processes." (PMID 36092891, 2022). "Overexpression of eIF4E, p-eIF4E and MNKs has been found in various cancers, promoting cell proliferation, inducing cell migration and invasion, and regulating tumor microenvironment (TME) by increasing the secretion of proinflammatory cytokines." (PMID 35877722, 2022). "eIF4E activation appears to be a critical event for Akt-mediated cancer development, whereas the activation of S6K downstream ribosomal protein S6 (rpS6) is dispensable for it." (PMID 36180910, 2022). "Increased expression of eIF4E has been observed in various cancers, which makes eIF4E an attractive target of anticancer drugs." (PMID 36225177, 2022). "Other relevant cancer targets, such as translational elongation and initiation factors (e.g., EIF4E), membrane receptors (e.g., EGFR), as well as RNA binding proteins, also showed a tendency towards better recovery, albeit not statistically significant." (PMID 35457260, 2022). "Consistent findings were obtained when detecting eIF4E in the obtained clinical tissue samples; namely, eIF4E was upregulated in carcinoma tissues compared with adjacent normal counterparts (P < 0.05)." (PMID 36225177, 2022). "eIF4E levels are increased in many cancers, where its elevation generally correlates with poor prognosis." (PMID 34944805, 2021). "Some eIF4E ASOs were designed also to recruit endogenous RNase H, therefore, decreasing eIF4E expression; studies performed using eIF4E ASOs on different cancer cell lines show promising results." (PMID 34541613, 2021). "PrognoScan, Kaplan–Meier plotter, and GEPIA were utilized to analyze the prognostic value of eIF4E in select cancers." (PMID 34876062, 2021). "Future research effort must be employed in designing and testing potential drugs against eIF4E, to evaluate the possibility of a cancer-specific drug." (PMID 35582305, 2021). "Although eIF4E overexpression is common in malignant tumors, changes in its transcriptional or protein level have little effect on translation." (PMID 34769253, 2021). "There are >15 ongoing trials using ribavirin to target eIF4E in cancer (see ClinicalTrials.gov (accessed on 25 November 2021))." (PMID 34944805, 2021). "Gene amplification and overexpression of eIF4E are found in many human cancers and correlate with tumorigenesis and progression, as well as with aggressive biological behaviors." (PMID 34876062, 2021). "eIF4E is often overexpressed and up-regulated in cancer cells, therefore it has been identified as a cancer marker and therapeutic target." (PMID 34344911, 2021).